AKR7L (aldo-keto reductase family 7 like (gene/pseudogene))
Description:
Can reduce the dialdehyde protein-binding form of aflatoxin B1 (AFB1) to the non-binding AFB1 dialcohol. May be involved in protection of liver against the toxic and carcinogenic effects of AFB1, a potent hepatocarcinogen (By similarity).
Synonyms: AFB1-AR 3; AFAR3; AKR7A4; AFB1-AR3
Gene: Protein-coding gene on chromosome 1 (19,265,982 to 19,274,194, reverse strand). Ensembl gene ENSG00000211454.
Subcellular location (Human Protein Atlas): Cytosol; Golgi apparatus
Pathways (Reactome):
Metabolism: Aflatoxin activation and detoxification
Genetic constraint (gnomAD): Missense variants: 171 observed, 204.48 expected, observed/expected ratio (o/e) 0.84, 90% interval 0.74 to 0.95. Synonymous variants: 60 observed, 75.5 expected, observed/expected ratio (o/e) 0.79, 90% interval 0.64 to 0.99.
Homologues: Orthologues: pig AKR7A2 (86% identical), mouse Akr7a5 (85% identical), dog AKR7L (84% identical), rat Akr7a2 (82% identical), guinea pig AKR7L (80% identical), rabbit AKR7L (76% identical), tropical clawed frog akr7a2 (66% identical), zebrafish akr7a3 (64% identical), Drosophila melanogaster CG6083 (22% identical), Caenorhabditis elegans C01G5.5 (20% identical), Caenorhabditis elegans Y39G8B.1 (20% identical), Caenorhabditis elegans F53F1.3 (19% identical), and 5 more. Paralogues in human: AKR7A3 (92% identical), AKR7A2 (89% identical), AKR1C3 (25% identical), AKR1C1 (25% identical), AKR1A1 (24% identical), AKR1C2 (24% identical), AKR1C8 (24% identical), AKR1B10 (24% identical), AKR1C4 (24% identical), AKR1D1 (24% identical), KCNAB1 (24% identical), KCNAB3 (23% identical), and 4 more.
Diseases named in the same sentence as AKR7L in open-access papers:
AKR7L is named in the same sentence as 2 diseases in open-access papers, as found by Europe PMC text mining. Sharing a sentence is not in itself a finding about the gene and the disease. The quoted sentences say what the papers report.
cancer (1 paper, 2015). A tumor composed of atypical neoplastic, often pleomorphic cells that invade other tissues. "However, some have been reported playing critical roles in cancer, such as H19, GUCY1B2, MEG3 and AKR7L." (PMID 25928635, 2015).
AKR7L also shares sentences with these, for which no sentence is quoted: tumor (1 paper).